LSAMP (limbic system associated membrane protein)
Description:
Mediates selective neuronal growth and axon targeting. Contributes to the guidance of developing axons and remodeling of mature circuits in the limbic system. Essential for normal growth of the hippocampal mossy fiber projection (By similarity).
Synonyms: IGLON3; LAMP
Tractability: Antibody: its Gene Ontology location is reachable by antibodies, with high confidence; UniProt places it where antibodies can reach, with medium confidence; UniProt predicts a signal peptide or a membrane-spanning region. PROTAC: its protein half-life has been measured.
Safety:
Unwanted effects reported when the protein is acted on. In parentheses: how it was acted on, where the effect was seen, and who reports it.
dermatitis (source: ClinPGx)
Gene: Protein-coding gene on chromosome 3 (115,802,374 to 117,997,592, reverse strand). Ensembl gene ENSG00000185565.
Subcellular location: Cell membrane
Subcellular location (Human Protein Atlas): Cytosol
Pathways (Reactome):
Metabolism of proteins: Post-translational modification: synthesis of GPI-anchored proteins
Gene Ontology:
Molecular function: protein binding
Biological process: heterophilic cell-cell adhesion; nervous system development; regulation of synapse assembly
Cellular component: cytosol; extracellular region; plasma membrane
Genetic constraint (gnomAD): Loss-of-function variants: 7 observed, 39.12 expected, observed/expected ratio (o/e) 0.18, 90% interval 0.1 to 0.34. The upper end of that interval is the gene's LOEUF score, 0.34, which puts it in group 1 of 6, group 1 being the genes least tolerant of losing a copy. Missense variants: 313 observed, 441.68 expected, observed/expected ratio (o/e) 0.71, 90% interval 0.64 to 0.78. Synonymous variants: 154 observed, 175.54 expected, observed/expected ratio (o/e) 0.88, 90% interval 0.77 to 1.
Homologues: Orthologues: macaque LSAMP (99% identical), mouse Lsamp (99% identical), pig LSAMP (99% identical), rat Lsamp (99% identical), chimpanzee LSAMP (95% identical), rabbit LSAMP (95% identical), tropical clawed frog lsamp (79% identical), dog LSAMP (78% identical), guinea pig LSAMP (54% identical), Drosophila melanogaster DIP-kappa (32% identical), Drosophila melanogaster DIP-eta (31% identical), Caenorhabditis elegans rig-5 (30% identical), and 10 more. Paralogues in human: NEGR1 (55% identical), OPCML (52% identical), NTM (52% identical), IGLON5 (46% identical), IGSF5 (15% identical).
Diseases named in the same sentence as LSAMP in open-access papers:
LSAMP is named in the same sentence as 48 diseases in open-access papers, as found by Europe PMC text mining. Sharing a sentence is not in itself a finding about the gene and the disease. The quoted sentences say what the papers report.
osteosarcoma (15 papers, 2010 to 2024). A usually aggressive malignant bone-forming mesenchymal neoplasm, predominantly affecting adolescents and young adults. "In these osteosarcoma models, survival analyses linked decreased LSAMP mRNA expression with worsened survival." (PMID 39595156, 2024). "A growing body of evidence has illuminated that LSAMP was inactivated and loss of expression due to DNA methylation modifications and acted as a tumor suppressor gene in osteosarcoma, acute myeloid leukemia, renal carcinoma and ovarian carcinoma." (PMID 35524253, 2022). "LSAMP is a tumor suppressor that is frequently inactivated in conventional osteosarcomas and linked to increased proliferation." (PMID 28484590, 2017). "The presence of a novel gene, limbic system-associated membrane protein (LSAMP), at 3q13.31 is suggested to have a significant tumour suppressive role in osteosarcoma." (PMID 22685381, 2012). "Our data agree with these findings and show significant loss of expression of LSAMP in the majority of our osteosarcoma samples." (PMID 20465837, 2010). "This region of copy number loss was shown to correlate with loss of expression and hypermethylation of the LSAMP gene, and the authors proposed LSAMP as a novel tumor suppressor in osteosarcoma." (PMID 20465837, 2010). "The characteristics of LSAMP defects and their association with aggressive and metastatic disease are evident in reports on clear cell renal cell carcinoma, prostatic adenocarcinoma, lung adenocarcinoma, osteosarcoma, neuroblastoma, acute myeloid leukemia, and epithelial ovarian cancer." (PMID 39595156, 2024). "LSAMP has been investigated for its tumor-suppressive role in osteosarcoma and was reported in several studies." (PMID 39595156, 2024). "A subsequent study further investigating LSAMP on chromosomal region 3q13.31 found reduced copy number of LSAMP in 59% of osteosarcoma samples and reduced expression of LSAMP in 60% of samples." (PMID 39595156, 2024). "Further, LSAMP expression in mouse osteosarcoma models resulted in significant delay in tumorigenesis." (PMID 39595156, 2024). "The methylation of the LSAMP promoter region was suggested as the epigenetic mechanism contributing to the decreased expression of LSAMP in osteosarcoma, as in RCC and lung adenocarcinoma." (PMID 39595156, 2024). "LSAMP has been known as a tumor suppressor gene in osteosarcoma and ovarian cancers; however, the evidence of LSAMP functions for lung cancer tumorigenesis is still lacking." (PMID 34202934, 2021). "A homozygous deletion of 3q13.31 carrying the LSAMP gene was seen in two of the six H3F3A mutant osteosarcomas." (PMID 28484590, 2017). "Another study on a dataset of 49 tumor biopsy tissues and DNA samples also identified locus 3q13.31 as the most common deletion in osteosarcoma, and an analysis of 43 tumor biopsies with the addition of 5 osteosarcoma cells lines demonstrated decreased LSAMP expression in over 64% of cases." (PMID 39595156, 2024). "LSAMP expression has also been shown to affect tumor growth and proliferation in osteosarcoma." (PMID 39595156, 2024). "We have summarized research articles reporting the role of LSAMP in the development of a variety of malignancies, such as clear cell renal cell carcinoma, prostatic adenocarcinoma, lung adenocarcinoma, osteosarcoma, neuroblastoma, acute myeloid leukemia, and epithelial ovarian cancer." (PMID 39595156, 2024). "LSAMP codes for a neuronal surface glycoprotein found in cortical and subcortical regions of the limbic system, but it is currently unclear how this gene may be related to osteosarcoma tumorigenesis." (PMID 20465837, 2010).
osteosarcoma (continued). "In neuroblastoma, LSAMP, as in RCC and osteosarcoma, appears to function as a tumor suppressor correlated with increased survival." (PMID 39595156, 2024). "Frequent deletions in the 3q13.31, including LSAMP and TUSC7, have also been identified in patients with osteosarcomas." (PMID 29736186, 2018). "H3F3A mutant osteosarcomas frequently showed a gain of chromosome arm 8q involving the c-MYC locus (3/6) and a distinct deletion of 3q13.31 involving LSAMP (2/6)." (PMID 28484590, 2017). "Two lncRNAs in the LSAMP tumor suppressor locus on chromosome 3q13, OC285194 and BC040587, were frequently focally deleted in osteosarcoma, often together with LSAMP." (PMID 24265805, 2013). "In the context of osteosarcoma, LSAMP has been frequently observed to be absent, which is strongly associated with tumor advancement." (PMID 39355132, 2024). "While we did not identify a correlation between LSAMP/LSAMP-AS3 copy number and expression, deletion of 3p13.31 has been associated with prognosis in multiple osteosarcoma studies and is significantly associated with event-free survival independently (p-value = 0.026) in our data." (PMID 35887382, 2022).
Anxiety (6 papers, 2013 to 2024). Intense feelings of nervousness, tension, or panic often arise in response to interpersonal stresses. "In murine studies, the loss of LSAMP expression was associated with decreased sensitivity to amphetamine, increased sensitivity to benzodiazepines, increased hyperactivity in new environments, abnormal social behavior, decreased aggressive behavior, and decreased anxiety." (PMID 39595156, 2024). "Complete deletion of LSAMP in genetic models leads to significant disruption of anxiety‐related behavior in the EPM, similar to hyperactivity." (PMID 33528889, 2021). "LSAMP (OMIM #603241) encodes a limbic system-associated membrane protein (LAMP) and has been shown to regulate anxiety-like phenotypes in mice." (PMID 24650298, 2014).
clear cell renal cell carcinoma (6 papers, 2008 to 2024). "Mutations in the NEGR1 gene have been related to Wilms tumor, which leads to malignant process in the kidney, additionally LSAMP promoter has been inactivated by methylation in a considerable amount of clear cell renal carcinomas." (PMID 28210208, 2017). "This was followed by another report that another IgLON, LSAMP, is also a TSG for renal clear cell carcinoma." (PMID 18714356, 2008). "This is consistent with another study where LSAMP was overexpressed in a clear cell renal cell carcinoma cell line without any evidence of apoptotic cells." (PMID 24885297, 2014).
major depressive disorder (6 papers, 2013 to 2023). An episode of depression lasting two or more weeks without an intervening episode of mania. "The neuronal growth regulator 1 (encoded by the gene Negr1) and the limbic system-associated membrane protein (encoded by Lsamp) have been shown to be expressed in the hypothalamus and to be involved in anxiety and depression-like behavior regulation." (PMID 36498834, 2022). "Nevertheless, it is of note that, in neuropsychiatric disorders, reduced expression of human LSAMP has also been described, and certain SNPs within the gene have been found to be associated with major depressive disorder." (PMID 36498834, 2022). "Certain SNPs that reside in the first intron flanking exon 1b of LSAMP are associated with major depressive disorder." (PMID 24633737, 2015). "Polymorphisms in the LSAMP gene have been associated with depression and LSAMP has been suggested to have a role in the neurobiology of male completed suicide." (PMID 24633737, 2015). "Moreover, an association was previously found between LSAMP gene polymorphisms and major depressive disorder, whereby patients presented with a significantly increased ratio between protective and risk LSAMP haplotypes compared to healthy volunteers." (PMID 35892672, 2022). "Moreover, we found an association between the gene polymorphisms of LSAMP and major depressive disorder (MDD)." (PMID 23532449, 2013). "Further in-group analysis of patients revealed that lower expression of certain IgLON genes, mostly LSAMP transcripts, could be related with concurrent depression-related factors in schizophrenic patients." (PMID 29434535, 2018). "Our recent studies indicate that the LSAMP gene is possibly related to major depressive disorder (MDD) and PD." (PMID 23532449, 2013).
ovarian carcinoma (5 papers, 2021 to 2024). A malignant neoplasm originating from the surface ovarian epithelium. "LSAMP has been linked to ovarian cancer, similar to the IgLON family member OBCAM, where the pathophysiology of the disease is better understood." (PMID 39595156, 2024). "Interestingly, high levels of LSAMP expression were seen in moderately differentiated and well-differentiated ovarian cancers, but were associated with decreased overall survival." (PMID 39595156, 2024). "A study suggests that high expression of LSAPM in ovarian cancer can serve as a specific target for ovarian cancer immunotherapy.Our study has found that LSAMP is highly expressed in extrahepatic cholangiocarcinoma tissues and it is highly correlated with patient prognosis." (PMID 39355132, 2024). "RCC, prostatic adenocarcinoma, AML, and ovarian cancer have stratified genetic risk factors by ancestry, but other cancers have not investigated the role of LSAMP or other significant factors in the context of the ancestries of patients." (PMID 39595156, 2024).
colorectal cancer (4 papers, 2021 to 2025). A primary or metastatic malignant neoplasm that affects the colon or rectum. "Therefore, a crucial role was demonstrated for the HMGA2–miRNA-200c-3p–LSAMP–Wnt pathway in the immune response to colorectal cancer, with significant implications for improved therapeutic responses." (PMID 39057097, 2024). "The mechanism of LSAMP-mediated protection was shown to be based on LSAMP inhibition of the Wnt–β-catenin signalling pathway, which is dysregulated in immune evasion and metastasis of colorectal cancer." (PMID 39057097, 2024).
acute myeloid leukemia (3 papers, 2018 to 2024). Acute myeloid leukemia (AML) is a group of neoplasms arising from precursor cells committed to the myeloid cell-line differentiation. "The authors also showed that, although the patient with acute myeloid leukemia had a 250-kb deletion in 3q13.31, which included the TUSC7 gene but not LSAMP, the expression of both genes was increased by an unknown mechanism." (PMID 29736186, 2018).
coronary artery disease (3 papers, 2016 to 2021). "LSAMP has been shown to influence smooth muscle cell proliferation, and LSAMP variants are associated with survival in coronary artery disease patients." (PMID 34895303, 2021). "Interestingly, LSAMP down-regulation in coronary artery diseases is associated to atherosclerosis burden." (PMID 27317124, 2016). "Furthermore, NEGR1 has been found to control endothelial integrity in human brain microvessels; LSAMP has been shown to be implicated in the coronary artery disease and both LSAMP and OPCML have been shown to be implicated in the epithelial-mesenchymal transition." (PMID 34203377, 2021).
lung carcinoma (3 papers, 2021 to 2023). "Furthermore, the loss of function of LSAMP in lung cancer enhanced cellular migration via EMT under the epigenetic regulation of DNA hypermethylation and miR-141-3p." (PMID 34202934, 2021). "Based on these expression profiles, LSAMP was the most significant gene linked to lung cancer." (PMID 34202934, 2021). "According to our results, the expression of Lnc-LSAMP-1 in lung cancer tissues is highly related to the LSAMP expression level, supporting the modulating role in cis of Lnc-LSAMP-1 to LSAMP." (PMID 35524253, 2022). "In this study, we also found a decreased expression of LSAMP in lung cancer, which was in accordance with previous study." (PMID 35524253, 2022). "LSAMP expression was lower in lung tumor parts than in lung normal parts from six lung cancer patients." (PMID 34202934, 2021). "Our result showed for the first time that LSAMP acts as a potential tumor suppressor in regulating lung cancer." (PMID 34202934, 2021). "A further deep investigation into the role of LSAMP in lung cancer tumorigenesis would provide therapeutic hope for such affected patients." (PMID 34202934, 2021). "Based on above information, LSAMP may function as a tumor suppressor gene in lung cancer progression, and it is reasonable to speculate that Lnc-LSAMP-1 influences a variety of cellular biological behaviors by regulating LSAMP gene." (PMID 35524253, 2022). "Based on our study results, LSAMP acts as a suppressor in lung cancer tumorigenesis and LSAMP might be of great potential in developing a therapeutic strategy to overcome lung cancer." (PMID 34202934, 2021). "The specific characteristic of LSAMP as a CAM might explain its function in lung cancer progression." (PMID 34202934, 2021). "Our study indicated that LSAMP acts as a suppressor in lung cancer tumorigenesis." (PMID 34202934, 2021). "Consistent with the transcriptome data, SERPINE2 was more highly expressed in lung cancer tissues compared with that in paratumor tissues, while a low expression of FGF10, LSAMP, and PDE5A was found in lung cancer tissue." (PMID 37280069, 2023). "The aggressiveness of cancer shortens survival time in cancer patients and based on the survival data, lower expression of LSAMP but not NTM conferred shorter survival time in lung cancer." (PMID 34202934, 2021). "With the aid of shRNA knockdown in a lung cancer cell line, A549, LSAMP did not affect cell proliferation through BrdU incorporation, tumor spheroid formation, nor stem cell characteristics." (PMID 34202934, 2021). "Firstly, with only six paired samples, a definite conclusion for the role of LSAMP in lung cancer might not be reachable." (PMID 34202934, 2021). "However, with this solid molecular evidence, this study provides the role of LSAMP in LUAD tumorigenesis and might offer hope for lung cancer patients." (PMID 34202934, 2021).
panic disorder (3 papers, 2008 to 2024). An anxiety disorder characterized by multiple unexpected panic attacks with persistent concern of recurring attacks. "Additionally, polymorphisms in the limbic system-associated membrane protein (LSAMP) gene have shown strong associations with MDD and suggestive associations with panic disorder, suggesting a potential role for LSAMP in mood and anxiety disorders." (PMID 38888950, 2024). "Furthermore, in humans, polymorphisms of LSAMP were also associated with MDD, panic disorder, and neuroticism." (PMID 39457114, 2024). "Up to now, there has not been many published studies about LSAMP and human behaviour, although we have found some evidence about LSAMP polymorphisms being associated with panic disorder." (PMID 18433483, 2008).
prostate carcinoma (3 papers, 2019 to 2024). A carcinoma that arises from epithelial cells of the prostate gland. "Prostatic adenocarcinoma studies linked LSAMP aberration with prostate cancer in AA patients, and with disease progression more frequently in AA patients." (PMID 39595156, 2024). "A study conducted on analyses of 435 prostate cancer patients established a significant association between defects in the LSAMP gene and tumors of African ancestry." (PMID 39595156, 2024). "A growing body of evidence points to how the LSAMP gene functions in prostate cancer, as well as other cancers, and the role of LSAMP in tumor suppression." (PMID 39595156, 2024). "An analysis of structural variations in 180 prostate cancer tumors identified LSAMP as a candidate driver gene and possible prognostic target for AA tumors." (PMID 39595156, 2024). "LSAMP encodes a cell-surface glycoprotein and has a possible tumor suppressor role in several cancers; notably, deletions near the LSAMP locus have been shown in one report to be enriched in African American men with prostate cancer." (PMID 35943799, 2022). "A high frequency (20%) of LSAMP deletion was reported also by Ren and coworkers in a Chinese cohort of prostate cancer patients." (PMID 31366128, 2019). "In addition to alterations in highly validated prostate cancer genes, we identified highly recurrent rearrangements near or involving genes that have not been extensively studied in prostate cancer in multiple cohorts, such as LSAMP, PTPRD, and TTC28." (PMID 35943799, 2022). "In prostate cancer cell culture model experiments, the absence of LSAMP affected RTKs and activated both the ERK and Akt pathways and downstream β-catenin through RAS signaling." (PMID 39595156, 2024). "Frequent gene transecting alterations were observed at the TTC28 (37.1% of 143 samples), LSAMP (31.5%), and PTPRD (23.8%) loci, which have not been extensively studied in prostate cancer, though they have been reported in callsets for certain cohorts." (PMID 35943799, 2022).